JUN (Jun proto-oncogene, AP-1 transcription factor subunit)
Diseases named in the same sentence as JUN in open-access papers (continued):
Sharing a sentence is not in itself a finding about the gene and the disease.
colon carcinoma (86 papers, 2000 to 2025). "Inhibition of p-AKT has previously been shown to increase TRAIL receptor expression in colon cancer and acute myelogenous leukaemia cells, which was associated with increased c-JUN expression." (PMID 30305055, 2018). "Previous studies revealed that USP28 is required for the stability of oncoproteins such as c-MYC in colon cancer 37-39, and c-JUN and NOTCH in colorectal cancer." (PMID 33664871, 2021). "Since the transcription factor c-JUN binds to Nanog promoter to express higher level of stem-like genes in human colorectal cancer, and MBD3 can repress c-Jun transcription in colon cancer cells, we analyzed c-JUN expression in iCSCs." (PMID 27894081, 2017). "JUN is overregulated in three of the five datasets and is related to: 1) colon cancer signaling pathways along with MYC; 2) the focal adhesion pathway along with ELK1; 3) pathways in cancer along with ELK1 and MYC; 4) EBV infection along with MYC; and 5) angiogenesis." (PMID 39228892, 2024). "Moreover, since it has been previously established that glutamine insufficiency invokes stress-activated JNK/c-JUN signaling, a study recently characterizes a lncRNA named GIRGL which is transactivated by c-JUN in colon cancer cells deprived of glutamine." (PMID 35842651, 2022). "Interestingly, FOS and JUN are present in gained enhancers in colon cancer, leading to implication in the differentiation, proliferation and apoptosis of colon cancer cells." (PMID 25477382, 2015). "Moreover, this group demonstrated that DACOR1 upregulation reprograms genome-wide DNA methylation in colon cancer cells, including gene promoters, gene bodies, and intergenic regions, leading to the inhibition of FOS and JUN and the repression of AP-1 activity in colon cancer cells." (PMID 33246471, 2020). "The remaining component of AP-1, JUN, is phosphorylated by the JNK cascade of RAS signaling, which is also active in colon cancer." (PMID 35159051, 2022). "In colon cancer, the expression of cheRNA DACOR1 is inhibited, and induction of DACOR1 leads to the remethylation of CpG islands at FOS and JUN promoter sites, thereby affecting the development of colon cancer." (PMID 33937246, 2021). "Colon cancer CaCo-2 and pancreatic cancer Panc28 cells were dosed with 40 μM of flavone A and levels of activated AKT, ERK, S6, and c-JUN were analyzed." (PMID 26606169, 2015). "Oncogenes including AKT1, JUN, SRC are a gene set that are also prominent in colon cancer." (PMID 30774816, 2018). "Finally, we find that ERN1 is an important regulator of JUN activity, which becomes crucial for survival in KRAS mutant colon cancer under conditions of abrogated MAPK signaling." (PMID 30482246, 2018). "The induction of tumour suppressor DACOR1 in colon cancer cells restores DNA methylation of thousands of CpG dinucleotides at hypomethylated sites in colon tumours including intergenic regions, promoters and gene bodies of oncogenic transcription factors such as FOS and JUN." (PMID 31430887, 2019). "The role of JNK-JUN signaling in resistance to MEK inhibitors is further supported by the finding that knockdown of JUN with shRNAs confers sensitivity to MEK inhibition and the notion that two different JNK kinase inhibitors synergize with MEK inhibition in breast and colon cancer cells." (PMID 29795445, 2018).
colorectal cancer (80 papers, 2009 to 2026). A primary or metastatic malignant neoplasm that affects the colon or rectum. "Previous research has reported that up-regulation of JUN is associated with the invasiveness of colorectal cancer cells." (PMID 36357874, 2022). "JUN activation enhances the phagocytosis of colorectal cancer cells by monocyte-differentiated macrophages." (PMID 40332792, 2025). "We suggest that the differentially expressed genes LMNB1 and JUN are potential targets for predicting colorectal cancer metastasis." (PMID 39390002, 2024). "It is possible that these molecules LMNB1 and JUN act alone as markers of early colorectal cancer metastasis, or in combination with each other, but this requires validation by clinicians in clinical therapies." (PMID 39390002, 2024). "JUN is involved in the transcriptional activation of USP28 in colorectal cancer (CRC) cells by activated KRAS." (PMID 36004808, 2022). "Activation of the Wnt/β-catenin signaling pathway drives colorectal cancer growth by deregulating the expression of many downstream targets, such as c-JUN, c-Myc, cyclin D1, CD44 and Axin2." (PMID 35065674, 2022). "The stabilized PDCD6/c-Raf complex subsequently activates the Raf/MEK/ERK signaling pathway and regulates the downstream transcription factors including MYC and JUN, which resulting in colorectal cancer growth and progression." (PMID 32746883, 2020). "LMNB1 and JUN are potential target genes for predicting colorectal cancer metastasis." (PMID 39390002, 2024). "Interestingly, IL-6 receptor levels have been reported to reflect OSA severity; FOS, FOSB, and JUN have been demonstrated to be involved in obesity, osteoporosis, and colorectal cancer; and DUSP1 is upregulated in CIH in OSA patients." (PMID 36468038, 2022). "Finally, up-regulation of JUN is related to the invasiveness of colorectal cancer cells." (PMID 26202601, 2015). "The increased activity of JUN (P < 1.00×10−278) triggers the activation of the c-Jun N-terminal kinase (JNK) and mitogen-activated protein kinase (MAPK) pathways in colorectal cancer." (PMID 40585960, 2025). "This screen established a relationship between ERN1 and JUN and highlighted the relevance of the ERN1-JNK-JUN pathway as a novel regulator of MEKi response in human KRAS-mutant colorectal cancer, providing a therapeutically exploitable vulnerability." (PMID 35740503, 2022). "JUN and FOS were involved in lots of pathways, including MAPK signaling pathway, PD‐L1 expression and PD‐1 checkpoint pathway in BC, colorectal cancer, and even coronavirus disease––COVID‐19 pathway." (PMID 35037412, 2022). "Notably, conserved overexpression of JUN/FOS (AP-1 complex) and ITGB1 was observed across all three cancer types and colorectal cancer, underscoring their roles as shared molecular drivers." (PMID 40725477, 2025). "JUN is involved in pathways like Toll-like receptor 3 (TLR3) signaling and prolactin signaling and plays a role in transcriptional activation of USP28 in colorectal cancer." (PMID 40092686, 2025). "Interestingly, data from the literature indicate that, in gastric and colorectal cancer cells, MAPK15 can directly phosphorylate JUN on Ser63/73." (PMID 40507959, 2025). "In colorectal cancer (CRC) cells, JUN is involved in USP28 transcriptional activation." (PMID 40092686, 2025).
gastric cancer (76 papers, 2009 to 2025). A primary or metastatic malignant neoplasm involving the stomach. "The study indicates that inhibition of CAMKK2 has an anti-oncogenic effect in gastric cells regulating phosphorylation of STAT3 through PTK2/c-JUN in gastric cancer." (PMID 35646067, 2022). "We note that key nodes such as COL1A1, COL1A2, JUN, MMP9, APOE, and FOS displayed strongest strength of interactions in the network, suggesting that these genes are key genes associated with other proteins in gastric cancer." (PMID 39044041, 2024). "A more detailed understanding about the role of CAMKK2 in activation of the tyrosine phosphoproteome and, in particular, PTK2/JUN/STAT3 signaling in gastric cancer is needed, in addition to functional studies in preclinical models, which is beyond the scope of this article." (PMID 35646067, 2022). "This indicates that CAMKK2-mediated signaling may orchestrate through PTK2/JUN/STAT3 signaling in gastric cancer." (PMID 35646067, 2022). "Intriguingly, the integrative predictive model hinging upon the genetic signatures of JUN, HIF1A, and PTGS2 emerges as a robust prognostic indicator correlating with poorer clinical outcomes in gastric cancer patients." (PMID 40391580, 2025). "In the realm of clinical translation, we leveraged the genetic signatures of JUN, HIF1A, and PTGS2 to establish a predictive model tailored for gastric cancer prognosis." (PMID 40391580, 2025). "The authors found a subgroup of cells between the metastatic group and primary group and discovered some gastric cancer lymph node metastasis marker genes (ERBB2, CLDN11, and CDK12), as well as potential gastric cancer evolution-driving genes (FOS and JUN)." (PMID 37612741, 2023). "In conclusion, linc01133, a JUN and FOS regulated lncRNA, promoted gastric cancer cell growth as a ceRNA for miR-145-5p via YES1 mediated YAP1 nuclear translocation." (PMID 35017464, 2022). "Our data revealed decreased phosphorylation of PTK2, c-JUN, and STAT3 upon inhibition and siRNA-mediated silencing of CAMKK2 in gastric cancer cells." (PMID 35646067, 2022). "PPI network analysis showed that the main proteins through which CKI acts on gastric cancer cells include AKT1, IL6, MAPK1, and JUN." (PMID 35590327, 2022). "Our data provide a glimpse of CAMKK2-regulated tyrosine signaling in gastric cancer cells, which involves the PTK2/JUN/STAT3 axis." (PMID 35646067, 2022). "Our western blot data revealed decreased phosphorylation of PTK2 at Y925, p-c-JUN at S73, STAT3 at Y705, and AMPK at T172 upon both inhibition and silencing of CAMKK2 in gastric cancer." (PMID 35646067, 2022). "Collectively, these compelling findings underscore the pivotal role of the JUN, HIF1A, and PTGS2 genes as promising clinical prognostic markers for patients grappling with gastric cancer, heralding a paradigm shift in personalized prognostication strategies within the oncological landscape." (PMID 40391580, 2025). "Furthermore, the prognostic models constructed by the carcinogenic genes JUN, HIF1A, and PTGS2 are significantly correlated with the survival time of gastric cancer patients." (PMID 40391580, 2025). "Furthermore, we detected the expression of c-JUN and c-FOS by immunohistochemistry (IHC) on human gastric cancer tissues." (PMID 35017464, 2022). "Moreover, to determine whether knockdown of c-Jun inhibited the mRNA and protein expression of LAMB1 in gastric cancer, we treated AGS and MKN-28 cells with JUN-specific siRNAs and found that c-Jun knockdown decreased LAMB1 expression at both mRNA and protein levels in AGS and MKN-28 cells." (PMID 33435161, 2021). "Simultaneous overexpression of JUN and FOS leads to stably increased linc01133 expression in MKN45, HGC27 and SGC7901 but not in AGS gastric cancer cells." (PMID 35017464, 2022).
gastric cancer (continued). "FOS and JUN overexpression increased linc01133 mRNA level in MKN45, SGC7901 and HGC27 gastric cancer cells, but not in AGS cells." (PMID 35017464, 2022).
prostate carcinoma (72 papers, 2004 to 2026). A carcinoma that arises from epithelial cells of the prostate gland. "Recent studies have shown that JUN facilitates the senescence-associated secretory phenotype and the recruitment of immune cells, contributing to the prevention of prostate cancer progression." (PMID 40092686, 2025). "We found groups that contained within them known associations among the transcription factors associated with prostate cancer-relevant signaling pathways, such as JUN and FOS, both member of the MAPK signaling pathway (oTFCG3)." (PMID 30314329, 2018). "Although most transcriptional regulators are present in the nucleus at levels below the LC-MS/MS detection limit, unbiased proteomics documented reductions in YAP and JUN (Dataset EV7), nuclear proteins linked to prostate cancer progression and recurrence." (PMID 40588551, 2025). "Elevated JUN levels characterized early-stage prostate cancer and predicted improved survival in human and murine samples." (PMID 38811984, 2024). "Our results suggest that JUN acts as tumor-suppressor and decelerates the progression of prostate cancer by transcriptional regulation of senescence- and inflammation-associated genes." (PMID 38811984, 2024). "We analyzed JUN expression in clinical prostate cancer samples across different stages and investigated its functional role in a Pten-deficient mouse model." (PMID 38811984, 2024). "Another report showed that miR-30d promotes angiogenesis and tumor growth of prostate cancer cells via the MYPT1/c-JUN/VEGFA pathway." (PMID 33824274, 2021). "It has been reported that GT3 treatment of prostate cancer LNCaP and PC3 cells causes upregulation of activated JNK and its target c-JUN via the downregulation of Id-3 and upregulation of MKK4." (PMID 32414345, 2020). "Almost all known transcription targets activated by the Wnt/β-catenin pathway, e.g. CTNNB1, CCCNDs, MMPs, PITX2, CD44, APCDD1, JUN, remain unchanged or are down-regulated in prostate cancer tissue or cell lines compared to normal tissue or cell line." (PMID 20454608, 2010). "c-JUN is a recognized master regulator of apoptosis in prostate cancer." (PMID 32414345, 2020). "Apoptotic effects involving the activation of both, c-JUN and ERK have been previously observed in LNCaP and PC3 prostate cancer cells treated with isothiocyanates, compounds present in cruciferous vegetables." (PMID 32414345, 2020). "Mechanistically, PAGE4 promoted the survival of prostate cancer cells through regulating MAPK pathway which reflected in decreasing the phosphorylation of MAP2K4, JNK and c-JUN but increasing phosphorylation of ERK1/2." (PMID 30658679, 2019). "In prostate cancer, phosphatase and tension homolog (PTEN) is responsible for the induction of NRP2 through the JUN N-terminal kinase (JNK)-JUN pathway." (PMID 30871059, 2019). "Meanwhile, ATO has been demonstrated to be an inducer of JUN through regulating JNK and MAPK pathways in many cancers, such as bladder cancer, prostate cancer, NSCLC, liver cancer and endometrial cancer." (PMID 26655252, 2016). "Among these six, HLF, JUN, c-MYC, EGR1, SMAD1, and HIF1A, were also identified as PTEN-controlled TFs, and four, ESR2, MYB, RELA, and USF1, as prostate cancer-related TFs." (PMID 22347425, 2012). "The proto-oncogenes JUN and FOS are pivotal in prostate cancer progression and invasion." (PMID 35508982, 2022).
prostate carcinoma (continued). "Higher levels of JUN, MXD1, and AQP3 were associated with a better OS, and each of the three genes was upregulated by deslanoside, suggesting that JUN, MXD1, and AQP3 could mediate deslanoside’s anticancer effect in prostate cancer cells." (PMID 34830961, 2021). "Thus, the inhibition of cell viability by GT3 in prostate cancer cells requires the presence of the phosphorylated forms of ERK and c-JUN." (PMID 32414345, 2020). "AKT is an important target in prostate cancer therapy and modulates BAD, c-JUN and ERK." (PMID 32414345, 2020). "Liquid biopsy of exosomes isolated from patients with prostate cancer revealed that exosomes are enriched for genes that are hallmarks of prostate cancer, such as androgen receptor, kallikreins (KLK2), cyclin-dependent kinase inhibitor 1A (CDKN1A), KLK10, JUN, and B2M (β2 microglobulin)." (PMID 36726968, 2022). "However, c-JUN can be phosphorylated by kinases other than JNK, which may allow GT3 to evade prostate cancer cell resistance." (PMID 32414345, 2020).